PINK1 (PTEN induced kinase 1)
Diseases named in the same sentence as PINK1 in open-access papers (continued):
Sharing a sentence is not in itself a finding about the gene and the disease.
hepatocellular carcinoma (40 papers, 2019 to 2025). A malignant tumor that arises from hepatocytes. "Conversely, in other tumor types, such as hepatocellular carcinoma, agents like ketoconazole and sorafenib paradoxically promote mitophagy through the stabilization of PINK1 and recruitment of parkin, which can culminate in apoptotic cell death." (PMID 40943612, 2025). "In the context of hepatocellular carcinoma cells (HepG2), it has been shown that FA (100 μg/mL) enhanced apoptosis via increasing PINK-1, Parkin and reducing the MMP expression." (PMID 40487371, 2025). "Stomatin-like protein 2 (STOML2) interacts with and stabilizes PINK1, amplifying PINK1/Parkin-mediated mitophagy, which in turn promotes the growth and metastasis of hepatocellular carcinoma (HCC)." (PMID 39416788, 2024). "In hepatocellular carcinoma, PINK1 has been reported to contribute to chemoresistance of multitarget tyrosine kinase inhibitors." (PMID 39440945, 2024). "FOXO3 impaired PINK1 protein stability by driving BNIP3 transcriptional repression in hepatocellular carcinoma." (PMID 36823640, 2023). "PINK1 targets the intervention of mitogen-cox-2/drp1-dependent mitochondrial dynamics and increases hepatocellular carcinoma chemosensitivity." (PMID 37833780, 2023). "Previous studies have confirmed that enhanced mitophagy mediated by high PINK1 expression can significantly enhance the sensitivity of hepatocellular carcinoma cells to radiotherapy and lenvatinib." (PMID 36823640, 2023). "PINK1 promotes tumor cell proliferation, apoptosis, migration, and invasion in breast, gastric, colorectal, and liver carcinomas." (PMID 37833780, 2023). "Previous studies demonstrated that PINK1/Parkin dependent mitophagy can facilitate chemotherapy resistance in ovarian cancer, hepatic carcinoma, breast adenocarcinoma and lung cancer." (PMID 36387221, 2022). "Further, it has been shown that HEY1, a HIF-1 target, decreases mitochondrial biogenesis by repressing the expression of PTEN-induced kinase 1 (PINK1) in human hepatocellular carcinoma cells through a HIF-1–dependent mechanism." (PMID 36421698, 2022). "STOML2 was reported to potentiate metastasis of hepatocellular carcinoma by promoting PINK1-mediated mitophagy and regulating sensitivity to Lenvatinib." (PMID 36531021, 2022). "A recent study of hepatocellular carcinoma (HCC) suggested that mitophagy triggered by the accumulation of PINK1 and PRKN translocation can promote the apoptosis of HCC cells, suppressing the growth of patient-derived tumour xenografts." (PMID 34616772, 2021). "According to our current study, the main stimuli that promote mitophagy in hepatoma cells were the destruction of mitochondrial structure and the up‐regulation of PINK1/Parkin activation under CTB treatment." (PMID 31994339, 2020). "Our data support that the mitochondrial damaging effect of MKIs, such as sorafenib and regorafenib, is promoting mitophagy in hepatoma cells, being the PINK1/Parkin signaling pathway clearly enhanced by modifying the antioxidant defense, as BSO pre-incubation does." (PMID 34572967, 2021). "Icariin degrades mitochondrial DNA, reduces the protein expression of the PINK1–Parkin pathway, induces mitochondrial fragmentation, and acts synergistically with adriamycin to induce mitophagy and apoptosis to treat therapy-resistant hepatocellular carcinoma." (PMID 34065886, 2021). "uncovered that p‐Drp1Ser616 anchors to mitochondria‐lysosome MSC through combination with Rab7, which stimulates PINK1/Parkin‐mediated mitophagy and mitigates apoptosis in hepatocellular carcinoma (HCC) cells undergoing chemotherapy." (PMID 39668579, 2025). "In particular, PINK1-mediated mitophagy could play an indispensable role in improving the metabolic dysfunction-associated fatty liver disease (MAFLD) which could precede to steatohepatitis (NASH), fibrosis, and hepatocellular carcinoma." (PMID 36982539, 2023).
hepatocellular carcinoma (continued). "Ketoconazole activates the PINK1–Parkin mitophagy pathway by downregulating COX-2 expression, thereby promoting apoptosis in hepatocellular carcinoma HCC." (PMID 40750884, 2025). "CDK9 inhibitors repress the SIRT1-FOXO3-BNIP3 axis and the PINK1-PRKN pathway, thereby inhibiting mitophagy initiation and promoting mitochondrial dysfunction in hepatocellular carcinoma, which disrupts mitochondrial homeostasis and induces apoptosis." (PMID 40855568, 2025). "In the context of hepatocellular carcinoma cell (HepG2), it has been shown that FA (100 μg/mL) enhanced autophagy, with increasing Beclin-1, LC3-I/LC3-II, PINK-1, and Parkin and decreasing MMP expression." (PMID 40487371, 2025). "In addition, GLI1 editing promotes a metabolic shift to oxidative phosphorylation to sustain stemness through PINK1/Parkin-mediated mitophagy in hepatocellular carcinoma (HCC), therefore enhancing metastatic potential and sorafenib resistance of HCC." (PMID 39035027, 2024). "In mice, Parkin or PINK1 deletion promotes KRAS-driven pancreatic carcinogenesis and results in the development of hepatocellular carcinoma." (PMID 38262996, 2024). "Inhibition of CDK9 can block the initiation of PINK1-PRKN-mediated mitochondrial phagocytosis by regulating the SIRT1-FOXO3-BNIP3 axis and enhance the therapeutic effect of mitochondrial dysfunction in hepatocellular carcinoma." (PMID 38012584, 2023). "For example, through regulating PINK1-mediated mitophagy, STOML2 was found to promote cancer metastasis and lenvatinib resistance in hepatocellular carcinoma." (PMID 34774067, 2021). "In studies employing hepatocytes and hepatocellular carcinoma cells, the inhibition of mitophagy has been shown to increase fat droplet deposition, as indicated by the altered expression patterns of mitophagy indicators such as AMBRA1, Parkin, and PINK1." (PMID 40141351, 2025). "In hepatocellular cancer, STOML2 could directly bind with PINK1 and promote its subsequent mitophagy, which is different from our present study in pancreatic cancer." (PMID 36906621, 2023). "In hepatocellular carcinoma (HCC) cells, ketoconazole downregulates the expression of COX2, thereby triggering PINK1-Parkin-mediated mitophagy to enhance apoptosis, downregulate BCL2, BCL-XL and MCL1 and upregulate BAX and BAK." (PMID 39013891, 2024). "In addition, a recent study in hepatocellular carcinoma identified HIF-1 as a regulator of PINK1 and mitophagy by promoting STOML2-mediated mitochondrial PINK1 stabilization, but it is not known whether this mechanism is present in other tissues." (PMID 35387983, 2022).
breast carcinoma (39 papers, 2014 to 2025). "Metabolic stress in the MDA-MB-231 breast cancer cell line promotes PINK1-dependent packaging of mtDNA into EVs that are released via the Rab27 pathway, and these EVs alter invasive behavior of other tumor cells by activating TLR9 signalling." (PMID 40488669, 2025). "This process also elevates the expression of autophagy and mitophagy markers, including LC3 paralogs, BNIP3, and the PTEN-induced putative kinase 1 (PINK1)–Parkin pathway, in human breast cancer cell lines and mouse myoblasts." (PMID 40799515, 2025). "Nevertheless, another study proposed that PINK1-induced mitophagy, triggered by mitochondrial ROS (mitoROS), can initiate the sensitization of breast cancer cells to radiation." (PMID 39472438, 2024). "Our results reveal a differential dependence of DMT1 in MDA-MB-231 and T47D for PINK1/Parkin-dependent mitophagy, which is likely connected to distinct regulation of mitochondrial iron homeostasis across different breast cancer cell lines." (PMID 38184712, 2024). "In certain types of malignancy, e.g., ovarian and breast cancer, PINK1 plays the role of a tumor suppressor." (PMID 38612708, 2024). "It has been shown that flubendazole upregulates DRP1 expression and results in excessive mitophagy through PINK1/parkin signaling in breast cancer cells." (PMID 39472438, 2024). "There is evidence that the upregulation of MRPL52 promotes protective mitophagy through the PINK1/Parkin pathway, which helps breast cancer cells survive under hypoxic conditions." (PMID 39472438, 2024). "MUC1 degrades ATAD3A by inducing ubiquitination and promotes mitophagy in a Pink1-dependent manner, thereby inducing breast cancer progression." (PMID 36831455, 2023). "Recently, PINK1 has gained increased attention as an essential modulator of the cell cycle in cancers, including glioblastoma, melanoma, and breast cancer, among others, suggesting its prospective role in tumorigenesis." (PMID 36823640, 2023). "It has been reported that silencing PINK1 can effectively inhibit lung cancer and breast cancer cell proliferation and induce tumour cell apoptosis both in vivo and in vitro." (PMID 36823640, 2023). "As a result, the accumulation of full-length Pink1 on the mitochondrial outer membrane triggers mitophagy by inducing phosphorylation of Ub-Ser65, which augments breast cancer oncogenicity." (PMID 36289190, 2022). "Our results suggested that MUC1/ATAD3A/Pink1 axis-mediated mitophagy improved cancer cell proliferation, mammosphere formation, and tumor growth, suggesting a tumor-promoting role in breast cancers." (PMID 36289190, 2022). "Altogether, these data suggest that flubendazole stimulates mitophagy via PINK1/Parkin signaling in breast cancer." (PMID 35440104, 2022). "We also performed immunohistochemistry to assess BRCA1, PINK1, and Parkin expressions in breast cancer tissues derived from patients." (PMID 33888730, 2021). "Strikingly, BRCA1 and PINK1/Parkin expression were inversely correlated in cancerous mammary glands from breast cancer patients." (PMID 33888730, 2021). "We found that in breast cancer cells, the mitochondrial targeting reagents, which all induce mitochondrial depolarization along with PINK1 upregulation, induced proteasomal BRCA1 degradation." (PMID 33888730, 2021). "Our results showed that PINK1/Parkin-mediated mitophagy was activated in breast cancer cells after treatment with warangalone for 12 h." (PMID 33929971, 2021). "Our analyses showed that PINK1 played a protective role in five cancer types, including blood cancer, brain cancer, breast cancer, lung cancer, and soft tissue cancer." (PMID 33244455, 2020). "Our study describes a mechanism by which PINK1 mediates the complex balance between polyphyllin I-induced mitophagy and mitochondrial fission-mediated apoptosis in breast cancer cells." (PMID 28060722, 2017). "It has been shown that PINK1 silencing increases hydrogen peroxide-induced apoptosis in breast cancer cells." (PMID 28060722, 2017).
breast carcinoma (continued). "Inhibition of mitochondria specific autophagy (mitophagy) through PTEN inducible putative kinase 1 (PINK1) silencing restored antiestrogen sensitivity to resistant breast cancer cell lines." (PMID 26157705, 2015). "As we do not know the precise role of cytosolic PINK1 versus mitochondrial PINK1 in ER + breast cancer, we cannot exclude the possibility of both cytosolic and mitochondrial PINK1 contributing to the antiestrogen resistance phenotype." (PMID 25699171, 2014). "We also showed in our original manuscript that knockdown of PINK1 restores antiestrogen sensitivity to LCC9 breast cancer cells, further indicating a possible role of mitophagy in maintaining an endocrine therapy resistant phenotype." (PMID 25699171, 2014). "Further experimentation is needed to determine the role of parkin, PINK1, and mitophagy in antiestrogen resistance and breast cancer survival, which was outside the scope of our original short report." (PMID 25699171, 2014). "On the other hand, PINK1 has shown context-dependent effects, promoting cell migration and proliferation in lung cancer while exhibiting a protective role in other malignancies such as blood, brain, and breast cancers." (PMID 40243539, 2025). "Furthermore, in breast cancer, PINK1 expression has been significantly correlated with histological grade, and its depletion induces a distinct proteomic profile, particularly impacting energy metabolism pathways." (PMID 40565152, 2025). "PINK1/Parkin-mediated mitophagy can regulate breast cancer malignancy." (PMID 38184712, 2024). "Since PI3K/Akt signaling is abnormally activated in breast cancer and its activation is associated with cancer progression, targeting cytosolic PINK1 might serve as a promising therapeutic approach against breast cancer in the future." (PMID 39472438, 2024). "Likewise, in the HER-2 positive breast cancer subtype, inhibition of PINK1 expression has been found to enhance paclitaxel-induced apoptosis in BT-474 breast cancer cells." (PMID 39472438, 2024). "Although PINK1 is positively expressed in both normal breast tissue and breast cancer tissue, PINK1 exhibits diffuse cytoplasmic staining along with strong membrane staining in breast cancer, whereas, in normal breast tissue, it shows a granular cytoplasmic pattern and minimal membrane staining." (PMID 39472438, 2024). "This distinctive staining pattern indicated that the localization of PINK1 might be a new biomarker in breast cancer." (PMID 39472438, 2024). "The PINK1/Parkin pathway is currently a hotspot and was identified in breast cancer." (PMID 37610095, 2023). "Thus, PINK1 played a protective role in blood cancer, brain cancer, breast cancer, lung cancer, and soft tissue cancer and a detrimental role in colorectal cancer." (PMID 37047483, 2023). "In breast cancer, PINK1 could drive the production of extracellular vesicles containing Mitochondrial DNA (mtDNA), which promote invasiveness." (PMID 37940999, 2023). "Furthermore, higher BRCA1 expression and lower PINK1/Parkin expression were significantly correlated with poor recurrence-free survival rate in breast cancer patients." (PMID 33888730, 2021). "Furthermore, we confirmed that CRISPR depletion of PINK1 opposed release of CD63-postive EVs from cells derived from a mouse mammary carcinoma driven by the PyMT oncogene." (PMID 34623384, 2021). "In contrast to BRCA1, PINK1/Parkin was expressed at lower levels in breast cancer patients." (PMID 33888730, 2021). "Moreover, studies have indicated that PINK1 has cytoprotective and chemoresistant functions in breast cancer and that PINK1 can be used as a target for breast cancer treatment." (PMID 33981484, 2021). "Furthermore, knockdown of cofilin reduced mitochondrial fission and mitophagy through the indirect regulation of PINK1 (PTEN-induced kinase 1) in breast cancer cells treated with different compounds, which induce these mitochondrial processes." (PMID 33233365, 2020).
breast carcinoma (continued). "PINK1 also regulates apoptosis and cell growth in breast cancer cells." (PMID 28060722, 2017). "Moreover, deletion of PINK1 sensitizes MCF-7 breast carcinoma cells, as well as other cell lines, to mitochondrial-dependent apoptotic death stimuli." (PMID 28060722, 2017). "Whether PINK1 knockdown could also sensitizes breast cancer cells to polyphyllin I, we used shRNA to stably knock down PINK1 expression." (PMID 28060722, 2017). "Therefore, upregulating PD-L1 distribution in mitochondria through the PINK1-mediated mitophagy pathway might enhance the efficacy of anti-PD-L1 therapy for breast cancer." (PMID 39472438, 2024). "Specifically, in breast cancer (BRCA) and head and neck squamous cell carcinoma (HNSC), PRKN, PINK1, and MAP1LC3A were downregulated, while SRC and BECN1 were upregulated." (PMID 39859167, 2025). "For example, in breast cancer (BRCA) we found that OPTN, PINK1 and PRKN expression was positively correlated with infiltration of NK cells, while that of BECN1 was negatively correlated with it." (PMID 39859167, 2025). "MUC1 also enhances the invasiveness of breast cancer cells by disrupting ATAD3A and activating Pink1-related mitochondrial autophagy, revealing the critical role of the MUC1/ATAD3A/Pink1 axis in breast cancer progression." (PMID 38361923, 2024). "Mitochondrial-targeted deferoxamine (mitoDFO), induces PINK1-dependent mitophagy in hormone-dependent MCF7 and triple-negative MDA-MB-231 breast cancer cells." (PMID 38184712, 2024). "In breast cancer, both the mitochondrial and nonmitochondrial localization of PINK1 have been shown to suppress MCF-7 cell (a luminal A cell line) growth in vitro." (PMID 39472438, 2024). "Deletion of PINK1 may make breast cancer cells sensitive to paclitaxel and NSCLC cells sensitive to cisplatin, while PINK1 overexpression can counteract this sensitization and result in chemical resistance." (PMID 36909198, 2023). "We have further shown that miR-195 enhances mitochondrial SOD-2 expression but does not affect PINK1 levels in breast cancer cells." (PMID 30932749, 2019). "To date, research on PINK1.AS in breast cancer has not been conducted." (PMID 38326441, 2024). "Notably, our results show that DMT1 silencing induces PINK1/Parkin-dependent mitophagy as well as FTMT in MDA-MB-231 but not in T47D breast cancer cells." (PMID 38184712, 2024). "In breast cancer, research has demonstrated that the mitochondrial protein UCP1 inhibits the metastasis and proliferation of TNBC cells in vitro and in vivo, and this effect has been attributed to the involvement of GSDME-mediated pyroptosis and PINK1/parkin-induced mitophagy." (PMID 39472438, 2024). "In summary, the present study reports a novel model in which MUC1/ATAD3A/Pink1 axis-mediated mitophagy plays a crucial role in maintaining the malignant properties of cancer cells, providing a novel therapeutic target for the management of MUC1-positive breast cancers." (PMID 36289190, 2022). "The results showed that Pink1 knockdown intensely constrained CCCP-induced cell proliferation and mammospheres formation not only in MDA-MB-468 cells, but also in BT549 cells, indicating MUC1 facilitates breast cancer progression by promoting Pink1-dependent mitophagy." (PMID 36289190, 2022). "However, mitophagy-related proteins such as PTEN-induced putative kinase 1 (PINK1) and Parkin were unchanged in RSL3-treated PARPi-resistant breast cancer cells, indicating that RSL3 may induce non-selective autophagy, but not selective autophagy such as mitophagy." (PMID 41463402, 2025).